RNU6-127P (RNA, U6 small nuclear 127, pseudogene)
Gene: Small nuclear RNA gene on chromosome 2 (131,229,607 to 131,229,713, forward strand). Ensembl gene ENSG00000212199.
Homologues: Orthologues: macaque U6 (93% identical), macaque U6 (91% identical), guinea pig U6 (78% identical), dog U6 (75% identical), pig U6 (66% identical). Paralogues in human: RNU6-473P (99% identical), RNU6-617P (99% identical), RNU6-848P (99% identical), RNU6-1049P (98% identical), RNU6-1239P (97% identical), RNU6-1268P (97% identical), RNU6-816P (97% identical), RNU6-1021P (94% identical), RNU6-286P (93% identical), RNU6-631P (93% identical), RNU6-749P (93% identical), U6 (93% identical), and 1287 more.